PRL (prolactin)
Diseases named in the same sentence as PRL in open-access papers (continued):
Sharing a sentence is not in itself a finding about the gene and the disease.
tumor (continued). "In this nationwide study of 84 patients with giant prolactinomas followed for a median of 9 years after diagnosis, most of the patients had a good outcome of treatment, with long-term normalization of PRL achieved in over half of the patients and a significant tumor response in almost 70%." (PMID 37403202, 2023). "The excessive secretion of ACTH, PRL, or GH, compared to NF PitNETs, did not increase the risk of tumor persistence or recurrence." (PMID 38023185, 2023). "The increase in PRL secretion quantity due to inhibition of the action of prolactin inhibiting factor by tumor compression to the hypothalamus might suppress TRH-stimulated PRL response." (PMID 37484278, 2023). "Three patients had GH(+)/PRL(+)/TSH(+) tumors and one had a GH(+)/PRL(+)/FSH(+) tumor." (PMID 38137536, 2023). "Also, basal PRL level at diagnosis was correlated with postoperative tumor diameter (p = 0.63, p < 0.001)." (PMID 38003353, 2023). "The tumor size stabilized, and serum prolactin levels decreased." (PMID 37529607, 2023). "The third approach resulted in a more significant reduction in prolactin levels and tumor size." (PMID 36950000, 2023). "Further research is required to determine whether tumor cells’ prolactin levels can be used as prognostic marker for FMC." (PMID 37626804, 2023). "However, the activation of the cAMP pathway exerts an antiproliferative effect in both NF-PitNETs and PRL-secreting tumor cells." (PMID 37370829, 2023). "In addition, the preoperative PRL levels in patients who underwent surgical removal for inadequate tumor shrinkage were significantly lower than those in the other groups." (PMID 37143054, 2023). "We also examined the relationship between prolactin secretion at diagnosis and tumor diameter." (PMID 37711900, 2023). "In a review of 12 studies of 309 patients with macroprolactinomas, including giant prolactinomas, treatment with cabergoline (CAB) was accompanied by normalization of PRL in 80% and significant tumor reduction in 87% of the patients, thus demonstrating a good response to DA even in larger tumors." (PMID 37403202, 2023). "Tumours were classified according to size (microadenoma, macroadenoma and giant pituitary adenomas), type (Prolactin, Growth Hormone, FSH/LH, ACTH and TSH) and grade (grade 1a: non-invasive, 1b: non-invasive and proliferative, 2a: invasive, 2b: invasive and proliferative, and 3: metastatic)." (PMID 37501881, 2023). "Pending validation of humanized mice, syngeneic mouse models continue to be essential to reveal the impact of PRL as well as other agents on inflammation and suppression of anti-tumor immunity, a critical step toward employment of the promise of immunotherapies for hormonally responsive cancers." (PMID 35784527, 2022). "A review from Brazil demonstrated that cabergoline induced prolactin normalization in 86% of treatment naïve prolactinoma patients overall (91% in patients with microadenoma, 83% in macroadenoma) and resulted in tumor shrinkage in 80% of treatment naïve macroprolactinomas." (PMID 36013562, 2022). "A significant reduction of prolactin level and size of tumor was seen after repair in one patient." (PMID 36337795, 2022). "Accordingly, it is worthwhile to begin treatment and monitor PRL values and tumor size." (PMID 35000899, 2022). "In addition, we found a significant positive correlation between prolactin level after surgery and tumor size before surgery, (OR: 5.29 (1.65, 8.92), p = 0006)." (PMID 35365091, 2022). "In very rare cases, PRL levels decrease in spite of tumor size increase." (PMID 35000899, 2022). "The ACTH-producing neoplasm (case 1) appeared to be well differentiated due to the relatively large cytoplasm, but the prolactin-producing neoplasm (case 2) had scanter cytoplasm and lacked other signs of lactotroph differentiation; therefore, it appeared to be a poorly differentiated neoplasm." (PMID 34669159, 2022).
tumor (continued). "One of the unresolved problems in the management of patients with hyperprolactinemia includes primary or, less frequently, secondary resistance to dopamine analogues, when standard doses of drugs fail to normalize the level of PRL and reduce tumor size by at least 50%." (PMID 37733390, 2022). "A lower level of PRL was correlated with a larger volume of the tumor." (PMID 35360427, 2022). "However, lifelong continuous DA therapy is required in almost all patients to maintain PRL suppression and prevent tumor regrowth." (PMID 35892862, 2022). "The authors concluded that lapatinib may control tumor growth and reduce prolactin in selected patients." (PMID 36013562, 2022). "The last MRI showed tumor regression, and the PRL level remained in the normal range." (PMID 35865778, 2022). "Furthermore, the results showed this group of patients had a smaller tumor diameter (7.4 ± 2.0 vs. 8.6 ± 1.6 mm), higher postoperative PRL level (p < 0.05), and lower postoperative remission rate." (PMID 35807204, 2022). "Moreover, a significant relationship was observed between preoperative tumor volume and postoperative prolactin level (OR: 0.006 (0.0008, 0.01), p = 0.02)." (PMID 35365091, 2022). "Therefore, in cases with persistent amenorrhea a thorough case-by-case evaluation is required, with very close monitoring of tumor size and PRL levels if estrogen therapy is prescribed, due to the potential estrogen-induced decrease of DA efficacy." (PMID 35000899, 2022). "Furthermore, the strict inclusion criteria for patients minimized the confounding variable of tumor compression as much as possible, making the PRL level the most important variable." (PMID 36009154, 2022). "Furthermore, in patients with prolactinomas, metformin was reported to be able to reduce PRL levels and shrink the tumor." (PMID 35721320, 2022). "A review of 13 case series involving 97 patients with giant prolactinomas treated with DA reported normalization of prolactin levels in 60%, a significant reduction (> 30%) in tumor size in 83%, and improvements in visual symptoms in 96% of those who presented with visual field defects." (PMID 35488355, 2022). "Although it is not statistically significant, more patients with positive expression of the PRL in the tumor in the remission group may also contribute to better results in those patients." (PMID 35612842, 2022). "This should be distinguished from dopamine agonist resistance, which is preferred when there is failure to normalize serum prolactin and/or achieve significant tumor shrinkage (in macroprolactinomas) despite good tolerance and concordance with standard clinical dosages." (PMID 35608811, 2022). "In resistant prolactinomas, PRL normalization could be achieved in 26% of patients with some degree of tumor shrinkage in 52% of them by receiving at least daily Cab therapy (>3.5 mg/week)." (PMID 35000899, 2022). "It has been reported that PRL plays a significant role in the proliferation of breast tissues and normal malignant tumor tissues, including enhancing the migration and proliferation of tumor cells, angiogenesis, sand apoptosis." (PMID 36591471, 2022). "Moreover, significant differences in sex ratio (33 vs. 69% of men), median PRL levels (818 vs. 4316 μg/L) and the maximal craniocaudal tumour diameter (18 ± 1 vs. 29 ± 6 mm) were observed between DA-sensitive and DA-resistant patients in this study." (PMID 35683457, 2022). "Given all these data, an early TRT may be suggested (within 3–6 months after the start of DA), provided that PRL levels are progressively decreasing and tumor size is shrinking." (PMID 35000899, 2022). "On the contrary, nursing caused neither an increase in PRL levels nor headaches or visual disturbances, which would suggest tumor enlargement." (PMID 35000899, 2022). "In addition, subtle differences in the structures of mouse/human proteins can obscure paracrine/systemic communication between tumor and stromal cells, e.g., PRL itself." (PMID 35784527, 2022).
tumor (continued). "Although suckling stimulates PRL secretion in normal women, there are no data to suggest that breastfeeding can cause tumor growth." (PMID 35000899, 2022). "Since, as proven in this study, the level of prolactin correlates with the level of neuropsychological deficit, and the level of prolactin depends on the tumor size, one could expect that the tumor size will also correlate with the deficit level." (PMID 36581642, 2022). "In prolactinomas, tumor volume usually correlates with serum PRL levels." (PMID 35892862, 2022). "Moreover, they demonstrated how the everolimus and cabergoline combination determined in vivo tumor size reduction and PRL level normalization." (PMID 35721701, 2022). "Additionally, PRL is produced by breast (tumor) cells and acts directly on the cell itself (autocrine) or adjacent cells (paracrine)." (PMID 36591471, 2022). "Tumor progression may occur in nearly 7% of patients with microP and PRL levels may reincrease in MP." (PMID 35000899, 2022). "A giant prolactinoma is defined as prolactinoma with a tumor >4 cm and very high serum PRL levels." (PMID 35892862, 2022). "Very preliminary data support that in some patients with DA-resistant MP, the addition of octreotide LAR or pasireotide LAR to ongoing Cab therapy may result in significant reductions in tumor volume and PRL levels." (PMID 35000899, 2022). "The PVR was calculated by dividing the preoperative prolactin level by tumor volume." (PMID 36147567, 2022). "Clinically, dopamine receptor agonists (DAs) (primarily bromocriptine [BRC] and cabergoline [CAB]) are the first-line treatment for the majority of patients with prolactinomas, and they effectively suppress prolactin secretion and shrink tumor volume in most patients." (PMID 33754007, 2021). "Importantly, effects of prolactin on expression of mesenchymal genes by the tumor parenchyma were very different in the absence and presence of Tregs." (PMID 34375938, 2021). "However, MRI in November 2013 demonstrated that the tumor size increased significantly, the serum prolactin level increased to 289.0 ng/mL again, and she received the second GKS treatment." (PMID 34715828, 2021). "On the other hand, they did not evaluate the different subtypes of single staining group, including the percentage of SG adenoma, also their single staining group had fewer acromegalic features, lower IGF-1, prolactin levels, and smaller tumor size compared with dual staining one." (PMID 34530798, 2021). "In addition, prolactin is an autocrine/paracrine factor that promotes tumor cell survival, proliferation and invasion." (PMID 34375938, 2021). "These patients with mutant prolactinomas displayed higher PRL levels and a shorter time in tumour development compared to patients without the mutation." (PMID 34681905, 2021). "The treatment goals for giant prolactinomas include normalization of PRL with recovery of altered pituitary axes, but, more importantly, reduction of tumor size with relief of compression of adjacent structures, particularly the optic chiasm and cranial nerves." (PMID 34771538, 2021). "Moreover, gefitinib suppressed serum PRL levels by 40%–50% and tumor volume by 30% in somatotroph adenoma xenografted rodent models." (PMID 33841328, 2021). "However, 10% of patients present DA-resistance, defined as a failure to normalize PRL levels or to achieve > 50% of tumor size shrinkage." (PMID 34173929, 2021). "utilized an antagonist peptide of PRL, G129R, which blocked the tumoral PRL/PRLR axis in orthotopic mouse models of human OCs, causing inhibition of tumor growth; they reported a synergistic effect of G129R with paclitaxel, which resulted in >90% lower tumor weights compared to controls." (PMID 34745013, 2021).
tumor (continued). "In prolactinomas, medical therapy relies on the preferential use of CAB compared to BRC because of the higher affinity of CAB to D2DR than BRC, its better tolerability profile, and its higher and long-lasting efficacy in normalizing prolactin (PRL) levels and in inducing tumor shrinkage." (PMID 35095761, 2021). "Our study indicated that PRL and PSEN1 were associated with tumor fibrosis and that prolactin might be the key cytokine regulating tumor fibrosis." (PMID 34539753, 2021). "PRL regulates tumor fibrosis, plays a promoting role in the growth and metastasis of ccRCC and may be a potential therapeutic target for ccRCC intervention." (PMID 34539753, 2021). "In addition, high miR-1299 levels in tumor cells can lead to high levels of prolactin synthesis and secretion and poor control of serum prolactin levels." (PMID 34046198, 2021). "PRL could induce carcinogenesis by regulating gene expression, for instance, CD24+, whose overexpression is associated with the tumor development and metastasis of human cancers." (PMID 34745013, 2021). "She experienced a loss of vision in the left eye, and MRI reported that the tumor volume increased significantly and compressed the optic chiasm, and the serum prolactin levels increased to 200.0 ng/mL (samples not diluted)." (PMID 34715828, 2021). "Several mouse tumor models have somatic KRAS alterations associated with increased p-ERK1/2, decreased signal transducer and activator of transcription 5 (STAT5), and variable PRL levels." (PMID 34572912, 2021). "Currently, cabergoline, a dopamine agonist (DA), is generally the first-line treatment of choice for prolactinomas, which reduces the size of tumor and normalizes PRL, leading to alleviation of endocrine and neurologic symptoms in 80–95% of patients during the first month of treatment." (PMID 34771538, 2021). "The actin binding protein filamin A (FLNA) is required for somatostatin receptor 2 (SSTR2) and dopamine receptor 2 (DRD2) expression and signaling in GH- and PRL-secreting PitNETs, respectively, playing a role in tumor responsiveness to somatostatin receptors ligands and dopaminergic drugs." (PMID 33664708, 2020). "In addition, PRL-PA-specific upregulation of genes caused by copy number amplification includes chromogranin B (CHGB), which has been linked to tumor progression in PRL-PAs, further supporting the role of genomic copy number variation in PA progression." (PMID 33472173, 2020). "Compared with the DRD2−/− mice, the plasma PRL levels in the peripheral blood (P < 0.01) and PRL mRNA expression levels in the pituitary gland (P < 0.05) were decreased, and the tumor/body weight ratio (P < 0.001) was decreased significantly in the DRD2−/−MAPK14+/− mice." (PMID 32894113, 2020). "However, drug resistance arises in a subset of patients, as indicated by a maintained prolactin level or tumor size." (PMID 33472173, 2020). "However, there was increased central tumor death with their combination that was more than additive at 250 ng S179D PRL and 220 pg calcitriol per hour." (PMID 33179012, 2020). "Of note, clinical management of hypogonadism in men with macroprolactinoma, which was refractive to dopamine agonists, required aromatase inhibitor treatment in addition to testosterone replacement, to prevent the secondary rise in PRL and, finally, the potential for tumor enlargement." (PMID 32188093, 2020). "Causes of resistance in this second group were: absence of prolactin normalization (5/11), < 50% tumour volume shrinkage (1/11) or the failure of both hormonal and tumour response (5/11)." (PMID 32429916, 2020). "In addition to direct effects on tumor cells, there was the possibility of a further synergy since both S179D PRL and calcitriol have been shown to be antiangiogenic." (PMID 33179012, 2020). "We assessed PRL secretions in culture media from mutant and wild-type culture tumor cells." (PMID 32427851, 2020).
tumor (continued). "There are in addition a very small number of cases where prolactin has been released from tissues that do not usually express prolactin and are most frequently associated with neoplasms of the female reproductive system." (PMID 32857272, 2020). "However, considering the possible detrimental effect of hyperprolactinemia as well as tumour volume, a reasonable definition is regarded as the failure to achieve prolactin normalization and/or a tumour size reduction in coronal surface of ≥50%." (PMID 32429916, 2020). "HCMV-induced production of PRL and its receptor may promote tumor growth in autocrine and paracrine manners." (PMID 32121009, 2020). "At this stage an alternative source of prolactin secretion was considered and since ectopic prolactin has been recognised as being a feature of neoplasms of the reproductive organs, further clinical assessment revealed a palpable pelvic mass in the lower abdomen rising to the umbilicus." (PMID 32857272, 2020). "One patient (PA11) had tumor with complementary prolactin expression." (PMID 33680922, 2020). "Previous studies have shown that PRL up-regulates BCL-2 expression in tumor cells." (PMID 33362552, 2020). "Compared with the estradiol-injected mice, the plasma PRL levels of peripheral blood (P < 0.01) and PRL mRNA expression levels in the pituitary gland (P < 0.05) were decreased, and the tumor/body weight ratio (P < 0.001) was significantly decreased in the estradiol-injected MAPK14−/− mice." (PMID 32894113, 2020). "Moreover, male patients have a higher serum PRL level and larger tumor volume in comparison with female patients with prolactinoma." (PMID 32188093, 2020). "PRL was shown to promote tumorigenesis by activating the Ras oncogene and by inducing malignant transformation in ovarian epithelial cells and enhanced tumor growth in SCID mice carrying mutations in tumor suppressor genes." (PMID 32121009, 2020). "Moreover, the scientists investigated in improvement cures to control tumor growth via reducing the prolactin production." (PMID 31742371, 2020). "For some immunoassays, if there are large analyte concentration ranges (such as with ferritin, growth hormone, hCG, PRL, Tg, and the tumour markers PSA, CA199, and CA125), antigen-antibody reactions can lead to an antigen excess, resulting in falsely decreased results and potential misdiagnosis." (PMID 33376621, 2020). "Also, both S179D PRL and calcitriol alone increased the number of apoptotic cells in tumor sections, but their combination reduced the number, suggesting more effective clearance of apoptotic cells." (PMID 33179012, 2020). "Resistant prolactinomas is generally defined as a failure to normalize prolactin levels or inability to induce tumor shrinkage despite the administration of more than 15 mg of bromocriptine daily for at least 3 months, or more than 1.5–2.0 mg of cabergoline weekly." (PMID 31191457, 2019). "Dopamine agonists, mainly bromocriptine (BRC) and cabergoline (CAB), are the first-line treatment for the majority of patients with idiopathic hyperprolactinemia and prolactinomas, and they effectively suppress prolactin secretion and shrink tumour volume in most patients." (PMID 31000722, 2019). "Removed microadenoma was classified as a PRL-secreting tumor." (PMID 31598814, 2019). "It has been found that, as in CC, there is an autocrine secretion of prolactin in the tumor cells, and the activation of PRLR triggers the signaling pathway of Src-ERK-AKT and phosphorylate the ERα inducing the activation and recruitment of the receptor to the ERE." (PMID 31507337, 2019). "Although it can be effective in controlling tumour growth, normalization of PRL is reported in only one third of patients, and it may require up to 20 years for maximal effects to be seen." (PMID 31847209, 2019). "Our findings suggest that the activation of the PRL/PRLR pathway may facilitate GBM tumour progression." (PMID 31862900, 2019).